MPO (myeloperoxidase)
Diseases named in the same sentence as MPO in open-access papers (continued):
Sharing a sentence is not in itself a finding about the gene and the disease.
renal disease (53 papers, 2014 to 2026). "Myeloperoxidase-specific anti-neutrophil cytoplasmic antibody-associated glomerulonephritis (MPO-ANCA GN) is a significant cause of renal disease, particularly rapidly progressive GN." (PMID 40735321, 2025). "The registry evaluated the predictive value of the ANCA serotype on renal outcomes and found a higher proportion of girls with renal disease and more cases with MPO-ANCA positivity compared to PR3-ANCA with associated renal involvement (n = 111, 88.1%, vs. n = 179, 77.2%)." (PMID 39769465, 2024). "Again, MPO-ANCA serotype was associated with more severe renal disease when compared with PR3-ANCA." (PMID 33909191, 2021). "A second interesting point is the significant association between higher anti-MPO antibody titers at the onset of pulmonary symptoms and the development of kidney disease in patients with MPO-ANCA ILD." (PMID 38445024, 2024). "In a renal ablation model simulating CKD, researchers compared MPO−/− mice with WT mice for the incidence of nephropathy." (PMID 38275657, 2024). "Although the prevalence of LAMP-2-ANCA has been debated in PR3/MPO-ANCA-associated vasculitis (AAV) and AAV-related kidney disease, overlapping seropositivity for LAMP-2-ANCA with MPO- or PR3-ANCA in SVV is consistently observed." (PMID 38612581, 2024). "Another study was conducted on eight MPO-AAV patients with severe renal disease treated with a CYC-free RTX regimen." (PMID 36552276, 2022). "SCG/Kj mice which were administered anti-apolipoprotein A-2 antibodies (anti-ApoA2) recovered from vasculitis related renal disorders and showed a decrease in the levels of MPO-ANCA and inflammatory cytokines." (PMID 36550471, 2022). "As found in recent literature, MPO-ANCA positive patients frequently have more advanced kidney disease at presentation and show a lesser likelihood of renal recovery following treatment." (PMID 33909191, 2021). "The neutrophil derived enzyme MPO is considered an important pathophysiogic factor in progression of renal disease." (PMID 28129740, 2017). "PR3 patients were younger, more frequent males but, in contrast with other studies, they presented with more severe kidney disease than MPO-ANCA patients." (PMID 27057255, 2014). "Patients with GPA who had MPO-ANCA had a numerically higher rate of renal disease (86.7%) than those with PR3-ANCA (41.7%)." (PMID 24758294, 2014). "Nonetheless, MPO-ANCA seropositive individuals were more likely to demonstrate improvement in kidney function (improved KDIGO category) within 1 year of diagnosis than PR3-ANCA seropositive individuals with similarly severe kidney disease at onset (p<0.001)." (PMID 38886004, 2024). "Multiple studies display the presence of MPO in a variety of renal diseases." (PMID 37020646, 2023). "Moreover, the transfer of MPO-specific CD8+ T cells into Rag1−/− mice prior to disease induction induced renal disease, while co-transfer of MPO-specific CD8+ T cells and CD4+ T cells worsened anti-MPO GN." (PMID 35626662, 2022). "Moreover, patients with MPO-ANCAs experience more severe renal disease at presentation, which is due to the increased frequency of chronic lesions in renal biopsy." (PMID 35127750, 2021). "Myeloperoxidase gene ablation prevents renal injury after surgical removal of the 4/5 of renal mass in the rat, and high myeloperoxidase levels are considered relevant for the progression of renal disease and cardiovascular complications in the CKD population." (PMID 29362665, 2017). "On the other hand, the severity of kidney disease at presentation could have offset the phenotypic differences between MPO and PR3." (PMID 26123651, 2015). "LAMP-2 has also been detected in adults with AAV-associated renal disease, with moderate to high LAMP-2 titres also found in 35% of paediatric systemic vasculitis cases involving small-medium vessels, with the highest concentrations in MPO- or PR3-positive individuals." (PMID 39769465, 2024).
renal disease (continued). "Relative to PR3-ANCA, MPO-ANCA seropositivity was associated with a higher likelihood of kidney involvement (OR 2.4, 95% CI 1.3 to 4.7, p=0.008) and severe kidney dysfunction (Kidney Disease Improving Global Outcomes (KDIGO) stages 4–5; OR 6.04, 95% CI 2.77 to 13.57, p<0.001) at onset." (PMID 38886004, 2024). "In a renal ablation model of CKD, MPO knockout mice displayed attenuated glomerular injury and decreased expression of markers of fibrosis and inflammation, suggesting that increased activity of MPO may contribute to kidney disease progression." (PMID 33477669, 2021). "Moreover, among MPO- and PR3-ANCA+ patients with renal involvement, those who are MPO-ANCA+ often present with more severe renal disease, characterized by a lower glomerular filtration rate, greater need for renal replacement therapy (31% vs. 20%), and more chronic appearing lesions on renal biopsy." (PMID 31867013, 2019). "Cystatin-C (Cys-C), myeloperoxidase (MPO), malondialdehyde (MDA), nitric oxide (NO), and superoxide dismutase (SOD) are involved with redox system and affect kidney diseases." (PMID 31049139, 2019). "In this cohort with MPO-ANCA dominance and severe kidney disease, male gender and the need for dialysis at presentation were significantly associated with PR3-ANCA when serum creatinine was above 5 mg/dL." (PMID 26123651, 2015). "MPO-ANCA levels at ILD diagnosis could warn on the progression to renal involvement in patients with MPO-ANCA ILD, hence caution is needed because renal disease can be subclinical or smoldering." (PMID 38445024, 2024). "In our study, we observed no significant change in the PON-1 and MPO activity along the progress of kidney disorders." (PMID 30857306, 2019). "We did not measure the concentration and activity of myeloperoxidase as an important source of reactive oxygen species in kidney diseases and numerous other chronic inflammatory disturbances." (PMID 30274359, 2018). "This is in contrast with other studies which reported similar or worse kidney disease at presentation in MPO-ANCA, not in PR3-ANCA." (PMID 26123651, 2015). "However, our data suggest that in regions where MPO-ANCA incidence is high, the possibility of severe kidney disease in PR3-ANCA patients in a nephrology setting should be kept in mind." (PMID 26123651, 2015). "Unlike MPO or PR3, a lesser known ANCA antigen, LAMP-2, is expressed on the surface of the renal microvascular endothelium and LAMP-2-ANCA have been detected in adults with AAV-associated renal disease." (PMID 33613565, 2020). "Although there is a high incidence of kidney disease in AAV, MPO and PR3 are not expressed by the glomerular endothelium, the primary site of injury in patients with renal involvement." (PMID 33613565, 2020). "Although our patient underwent examinations for differential diagnosis from other kidney diseases (IgG, IgA, IgM, C3, C4, cryoglobulin, PR3-ANCA, and MPO-ANCA), no clinically significant findings were obtained." (PMID 30646927, 2019). "Their utility as prognostic markers for renal disease, which has a high prevalence among patients with AAV, may have limitations given that MPO and PR3 are not expressed on the glomerular endothelium." (PMID 33613565, 2020).
bacterial infection (51 papers, 2009 to 2025). "Colonic MPO, an enzyme released by neutrophils recruited to the intestinal mucosa during bacterial infections and hallmark of colon inflammation, was also measured at the time of the necropsy." (PMID 38651930, 2024). "MPO was significantly associated with protein intake [β: −0.47; 95% CI: −0.69, −0.25], bacterial infection [β: 0.08; 95% CI: 0.02, 0.14], and diarrheal incidence [β: −0.17; 95% CI: −0.24, −0.11]." (PMID 35406021, 2022). "Researchers found that MPO-knockout mice were more susceptible to bacterial infection, and further experiments indicated that MPO could protect the host against Klebsiella pneumoniae." (PMID 38275657, 2024). "Moreover, MPO showed high activity in COM due to bacterial infection or physiological causes related to occlusion of the eustachian tube." (PMID 23756625, 2013). "The most frequently observed specificities in patients with GN bacterial infections caused by Klebsiella, P. mirabilis, or E. coli were PR3-ANCA and MPO-ANCA, with predominantly medium and low concentrations." (PMID 41008681, 2025). "We examined the inflammatory response of MPO‐/‐ mice with intestinal bacterial infection merely, hypoxia merely, and bacterial infection accompanied with hypoxia than those in wild‐type mice to explore the role of MPO in innate immunity." (PMID 38415976, 2024). "Here, we examined the inflammatory response of MPO‐/‐ mice with intestinal bacterial infection only, hypoxia merely, and bacterial infection accompanied with hypoxia to wild‐type mice to explore the role of MPO in innate immunity." (PMID 38415976, 2024). "The MPO plays an important role in innate immunity and has been indicated as a promising marker to evaluate the bovine immune function against bacterial infection." (PMID 39606644, 2024). "NGAL is synthesized as a component of the late granules of neutrophils, where it colocalizes with MPO, providing protection against bacterial infection by interacting with bacterial proteins, termed siderophores." (PMID 38005844, 2023). "These innate immune cells counteract bacterial infection mainly by phagocytosis and releasing lysozyme, ROS, elastase, and myeloperoxidase (MPO)." (PMID 37408838, 2022). "The activity of the neutrophil granular enzymes: elastase (NE) and myeloperoxidase (MPO) showed a significant increase in this fluid, especially NE during the second and third day of bacterial infection." (PMID 32183255, 2020). "Genes expected to have an increased expression during bacterial infection and neutrophil activation, such as IL-8 and myeloperoxidase, were down-regulated." (PMID 31861586, 2019). "The biological significance of this small initial difference is probably limited and soon after induction of secondary bacterial infection much higher MPO concentrations were measured in the lungs." (PMID 23483993, 2013). "While neutrophil activation may be adaptive to calibrate host defense against future bacterial infections, proteases and myeloperoxidase released upon degranulation have detrimental effects on the alveolar capillary barrier." (PMID 40475424, 2025). "The myeloperoxidase (MPO) enzyme plays an important role in protecting against the bacterial infections of fish, as macrophages can receive MPO from neutrophils, and this may enhance their bactericidal activity." (PMID 39682368, 2024). "Bacterial infection of the intestine and hypoxia can both lead to inflammatory responses, but the role of MPO in these phenomena remains unclear." (PMID 38415976, 2024). "Similarly, as an important marker of the inflammatory response, MPO is considered an important tool for diagnosing bacterial infections." (PMID 36776875, 2023). "First, we checked whether the myeloperoxidase activity, a main component of neutrophils to combat bacterial infection, was different between the huNSG mice and the control groups in the infected thigh muscle." (PMID 35795674, 2022).
bacterial infection (continued). "DAAO catalyzes the production of AHR agonists, including indole-3-pyruvic acid (I3P) though the enzymatic conversion of D-tryptophan to I3P, and is found in neutrophils which produce MPO and hypochlorous acid with immediate effect on the resilience to bacterial infection noted." (PMID 36499104, 2022). "Namely the nature of MPO determined its “dualistic role” in vivo—on the one hand, the ability to simultaneously protect the organism from various types of bacterial infection and, on the other hand, to attack the capillary network of blood circulation under certain conditions." (PMID 32908806, 2020). "In response to bacterial infection, neutrophils release neutrophil extracellular traps (NETs), which are web-like scaffolds of extracellular DNA decorated with histones and neutrophil granular proteins such as myeloperoxidase (MPO) and neutrophil elastase." (PMID 29945605, 2018). "Furthermore, H2O2 specifically is catalyzed by myeloperoxidase (MPO) to produce hypochlorous acid (HOCl) in the presence of bacterial infection as described in neutrophils." (PMID 28725637, 2017). "Myeloperoxidase (MPO), a heme-containing enzyme that catalyzes the production of free radicals and hypochlorite, is released by neutrophils during the inflammatory response to bacterial infections." (PMID 25698971, 2015). "MPO is involved in host defense and is released by neutrophils to help fight bacterial infections." (PMID 20799947, 2010). "These individuals are unable to modulate this response due to their precarious oxidative stress condition, shown by increased MPO activity, reduced PON activity, and higher susceptibility to lipid oxidation, which can favor bacterial infection and increase the risk of asthmatic crises." (PMID 19563660, 2009). "In addition, the results of immunofluorescence staining showed that Nano-MgB2 treatment significantly reduced the number of neutrophils (MPO-positive cells) and macrophages (F4/80-positive cells), indicating decreased bacterial infection and inflammation after Nano-MgB2 treatment." (PMID 36446788, 2022). "In addition, the changes in MPO activity showed a similar decreasing tendency, although with lower significance, when the comparison was made between the dual-species and mono-species bacterial infection." (PMID 32183255, 2020). "Investigations on bcl2 marker in gingival cells during periodontal inflammation we suggestion that periodontium tissues, continuously exposed to bacterial infections may contain cells with high level of myeloperoxidase results that damage DNA by product of catalysis." (PMID 26251029, 2015). "Surprisingly, however, myeloperoxidase deficiency does not lead to susceptibility to bacterial infections; the endogenous production of hydroxyl radicals by innate immune cells could potentially explain this observation." (PMID 20041108, 2009). "D-limonene in orange peel essential oil markedly improved rainbow trout’s total myeloperoxidase and SOD serum activities and enhanced the fish survival rate against bacterial infection." (PMID 39453066, 2024). "Myeloperoxidase (MPO) is an enzyme that is highly expressed in neutrophils and produces hypohalous acids in response to bacterial infection." (PMID 33352464, 2021). "Moreover, the inflammatory state alleviated by SEP was also reflected by a lower level of lung myeloperoxidase (MPO), a marker of neutrophilic inflammation following bacterial infection." (PMID 35370674, 2022). "MPO and ELA2 were detected only in the airways of P. aeruginosa infected mice and the concentration of these enzymes detected in the BAL fluid was significantly increased in the context of coinfection compared to bacterial infection alone." (PMID 31673002, 2019). "This is not surprising since the bacterial infection alone, which demonstrably lead to inflammation (as manifested by elevated levels of neutrophil myeloperoxidase), would lead to micro-bleeds and hence free haemoglobin." (PMID 25706529, 2015).
bacterial infection (continued). "In animals, it has been shown that neutrophil MPO concentrations may increase to double the normal level in non-fatal bacterial infections." (PMID 32442236, 2020). "The expression of ELANE, MPO and CD177 was not influenced by sex or the presence of bacterial infection." (PMID 34552111, 2021).
neurodegenerative disease (26 papers, 2013 to 2026). A disorder of the central nervous system characterized by gradual and progressive loss of neural tissue and neurologic function. "MPO is implicated in neurodegenerative disease and sarcopenia." (PMID 40565245, 2025). "The results suggest that the inhibition of MPO may provide a therapeutic option for PD and other neurodegenerative diseases in which MPO has been implicated." (PMID 36552550, 2022). "Increased levels of neuronal MPO have specifically been linked to neurodegenerative diseases." (PMID 33916434, 2021). "In neurodegenerative disease the role of MPO is crucial because it produces HOCl and HOCl and several HOCl-generated markers such as 3-chlorotyrosine have been identified in AD patients." (PMID 40565245, 2025). "Recently, we demonstrated a significant increase in neuroinflammation and MPO in XDP postmortem PFC, highlighting MPO as a contributor to this neuroinflammatory process similar to other neurodegenerative diseases." (PMID 39500625, 2024). "On the other hand, increased levels of oxidants by MPO can damage tissue damage and are found in many diseases characterized by acute or chronic inflammation such as cardiovascular and neurodegenerative diseases." (PMID 35239655, 2022). "The abnormal expression in neurons and glial cells in neurodegenerative diseases suggests that MPO can promote these diseases." (PMID 36552550, 2022). "Given the recent interest in the development of MPO antagonists for the treatment of neurodegenerative disease, our results also suggest that the pro-inflammatory effects of these agents should be closely monitored." (PMID 32758448, 2020). "This study discusses how ROS interacts with microglia in the striatum of patients with advanced neurodegenerative diseases based on the region-specific alteration in levels of microglial neurobiological phenotypes: MPO, PAR, and TREM2." (PMID 32842621, 2020). "Microglia in the neurodegenerative disease brains are positive for MPO, which is particularly increased in microglia, neurons, and β-amyloid (Aβ) plaques and not expressed in quiescent microglia in healthy brains." (PMID 32842621, 2020). "Given that MPO inhibitors are being developed for the treatment of neurodegenerative disease, our data suggest that the inflammatory side effects of these agents should be closely monitored during clinical trials." (PMID 32758448, 2020). "Among the mini-series, compound 28 (Ki σ1 = 0.2 nM, Ki σ2 = 198 nM, CNS MPO score = 5.4) emerged as a promising selective σ1 receptor ligand that warrants its further evaluation as a potential therapeutic for neurodegenerative diseases." (PMID 35540351, 2018). "Although MPO is rapidly released from activated neutrophils, monocytes, and some macrophages upon activation, MPO is also expressed by activated microglia, astrocytes, and certain types of neurons in neurodegenerative disease." (PMID 27220420, 2016). "MPO regulates MMP enzymes, which are associated with neurodegenerative diseases." (PMID 39950933, 2025). "While SCN− may not be a viable therapeutic itself for the treatment of PD due to toxicity issues, several other studies have hinted that MPO inhibitors can have a beneficial effect for the treatment of neurodegenerative diseases in humans." (PMID 36552550, 2022). "MPO is a heme-containing peroxidase and is expressed in neutrophils, activated microglia, astrocytes, neurons, etc., contributing to the neuropathology of multiple neurodegenerative diseases." (PMID 35178161, 2022). "MPO and MDA levels in brain tissue have been found to be elevated in numerous neurodegenerative diseases." (PMID 35970975, 2022). "Similarly myeloperoxidase (MPO) has been targeted due to its role in immune cell-mediated oxidative damage in MSA and other neurodegenerative diseases." (PMID 26860328, 2016).
connective tissue disease (15 papers, 2016 to 2026). "MPO (myeloperoxidase) participated in the regulation of mixed connective tissue disease progression." (PMID 38137330, 2023).